SETDB1 (SET domain bifurcated histone lysine methyltransferase 1)
Diseases named in the same sentence as SETDB1 in open-access papers (continued):
Sharing a sentence is not in itself a finding about the gene and the disease.
melanoma (continued). "SETDB1 methylates histone H3 on lysine 9 (H3K9) to accelerate melanoma formation significantly in zebrafish." (PMID 30544544, 2018). "It was previously reported that SETDB1 protein level was upregulated in human melanomas tissues and it enhanced the formation of melanoma in a zebrafish model." (PMID 30309377, 2018). "Previous studies have reported the SETDB1 overexpression in patients was detected in certain tumors such as melanoma and lung cancer." (PMID 29739365, 2018). "In a zebrafish melanoma model, overexpression of the histone methylase SETDB1 accelerates the onset of melanoma development." (PMID 28806732, 2017). "The 1q21 interval was later identified as a melanoma-susceptibility locus for familial melanoma, further demonstrating that SETDB1 is an oncogene in human melanoma." (PMID 28930163, 2017). "ATF7IP is a transcriptional cofactor that has been shown to be critical for heterochromatin formation by interacting with the histone methyltransferase SETDB1, an oncogene product promoting tumorigenesis in melanoma, lung cancer, and liver cancer." (PMID 29061142, 2017). "By screening the genes implicated in the rapid onset of melanoma, Zon and colleagues found that the overexpression of histone-lysine N-methyltransferase (SETDB1) can accelerate the onset and invasion of melanoma." (PMID 28718799, 2017). "The results also included 10 SNPs previously identified for melanoma risk reported at MC1R (2 SNPs), MX2, TERT/CLPTM1L, PLA2G6, CASP8, ACTRT3, ASIP, CDC91L1, and ARNT/SETDB1/LASS2ANXA9/MCL1/CTSK." (PMID 27993549, 2017). "In that study, all of the genes amplified in that human region were overexpressed in concert with BRAFV600E and it was found that only a single gene, SETDB1, contributed to melanoma pathogenesis." (PMID 28173755, 2017). "The results of the screen showed that a single gene, SET domain bifurcated 1 (SETDB1), a histone H3K9 methyltransferase, is able to cooperate with the BRAFV600E mutation and promote melanoma development." (PMID 28930163, 2017). "Among the different HAT, SETDB1 has been of increasing interest due to its recent involvement in melanoma, where it is located in a recurrently amplified chromosome fragment and in lung tumors." (PMID 26840455, 2016). "Screening for genes that promoted the rapid onset of melanoma, they discovered that overexpression of the histone methyltransferase SETDB1 can accelerate the onset and invasion of melanoma." (PMID 26354726, 2016). "Recent studies demonstrated that SETDB1 is frequently amplified in lung and urothelial cancers as well as melanoma." (PMID 25537518, 2015). "It is reported that SETDB1 is amplified in melanoma as well as in other cancer types including liver cancer." (PMID 26471002, 2015). "The copy number ranges for these genes varied widely, with NSD3/WHSC1L1 amplified at high copy number levels (5–15 copies) in breast cancer patients, while SETDB1 was amplified at 3–6 copy range in melanoma." (PMID 24874471, 2014). "A recent large-scale study identified a region spanning from MCL1 to SETDB1, as a key amplified region in malignant melanoma, and suggested SETDB1 as the target gene." (PMID 23825644, 2013). "This was motivated by the finding that overexpression of SETDB1 in an animal model resulted in accelerated melanoma onset and formation." (PMID 23825644, 2013). "SETDB1 is a histone methyltransferase and was previously shown to have oncogenic functions in melanoma, accelerating its formation." (PMID 23293768, 2012).
melanoma (continued). "SETDB1 exerts its function by methylation histone H3 at lysine 9 (H3K9), a modification linked to transcriptional repression, and its overexpression has been associated with increased melanoma formation." (PMID 40872623, 2025). "This suggests that SETDB1‐targeting strategies could be an effective addition to current melanoma treatments." (PMID 39764697, 2025). "Recent studies have shown that SETDB1 plays a significant role in melanoma pathogenesis." (PMID 39764697, 2025). "As SETDB1 is a recurrently amplified, established driver of melanoma, this raises the possibility that increased SETDB1 activity might have important metabolic consequences for melanoma." (PMID 37883365, 2023). "In addition, both mithramycin A and its analog (mithralog) EC-8042 effectively suppress SETDB1 expression in melanoma cells and enhance the efficacy of mitogen-activated protein kinase-inhibitor-based therapies for melanoma." (PMID 38057834, 2023). "SETDB1 has been found to be highly amplified in tumors of melanoma patients and melanoma cell lines, with overexpression contributing to a more aggressive phenotype in vivo and in vitro studies by upregulating thrombospondin 1 (THBS1) expression in a H3K4me1-dependent manner." (PMID 38057834, 2023). "Notably, a recent report revealed that SETDB1 promoted AKT activation to promote malignant melanomas progression by enhancing its methylation on K64." (PMID 35184652, 2022). "Moreover, a recent in vivo CRIPR-Cas9 screening in B16F10 cells highlighted the role of the histone methyltransferase SETDB1 in reducing the immunogenicity of murine melanoma cells, thus enhancing resistance to anti-PD-1 therapy." (PMID 35432344, 2022). "As an important participator of epigenetics, aberrant methylation at H3K9 induced by the histone methyltransferase SETDB1 may contribute to tumourigenesis in breast cancer, colorectal cancer, glioma, ovarian cancer, lung cancer and melanoma." (PMID 34299035, 2021). "Importantly, immunohistochemistry of human tissues showed that SETDB1 protein was highly expressed in melanomas as compared to benign nevi or normal melanocytes." (PMID 32455885, 2020). "Recent years, increasing evidence showed that abnormal expression of SETDB1 is closely related to tumorigenesis, including melanoma, lung cancer, breast cancer, and liver cancer, suggesting that SETDB1 is involved in the pathogenesis of a variety of human cancers." (PMID 32393761, 2020). "Finally, treatment with a small molecule inhibitor for H3K9me-specific histone methyltransferase to block the SETDB1 protein significantly decreased melanoma cell viability." (PMID 32042336, 2020). "SETDB1 is an oncogene in melanoma and underscores the role of chromatin factors in tumorigenesis." (PMID 30544544, 2018). "Recently, SETDB1 was reported as a novel oncogene in zebrafish melanoma model." (PMID 29739365, 2018). "High levels of SETDB1 are common in human melanoma, indicating that chromatin remodeling may be critical in melanoma progression due to changes in gene regulation, such as subset of homeotic genes (hox) genes." (PMID 28718799, 2017). "SETDB1 is an oncogene frequently amplified in human lung cancers and melanomas." (PMID 26824986, 2016). "Interestingly, SetDB1 is overexpressed in several cancers including human melanomas, and the SetDB1 gene is amplification in some lung tumors." (PMID 26405197, 2015). "SETDB1 significantly accelerated melanoma formation in a zebrafish model." (PMID 25537518, 2015). "Notably, both hnRNP K and SETDB1 have been identified as bona fide oncogenes and are aberrantly overexpressed in a variety of human cancers including melanoma, prostate carcinoma and lung carcinoma." (PMID 25611934, 2015). "While SETDB1-induced increase of H3K9 methylation exerts a prominent carcinogenic effect in established tumors, the restoration of H3K9 methylation by targeting LSD1 and JMJD2C abolishes the malignant transformation from melanocytes to melanoma driven by oncogenic mutations." (PMID 35693795, 2022).
melanoma (continued). "Therefore, SETDB1 has been confirmed as an oncogene in human melanomas and lung cancers." (PMID 34299035, 2021). "Similarly, this functional asymmetry in recruiting partners with controlled stoichiometry can be present for other KAP1 interacting partners engaged by the C-termini, such as SETDB1, or that interact with the CC domain, such as the melanoma antigen genes protein or KRAB-ZFPs." (PMID 31427381, 2019). "Intriguingly, H3K9 methylation regulated by SETDB1, LSD1, and JMJD2C appears to play quite opposite roles in the occurrence and development of melanoma." (PMID 35693795, 2022). "An independent study showed that SETDB1 cooperates with histone demethylase KDM5B/JARID1B to silence retroelements, which decreases antigen presentation in melanoma cells, efficiently promoting immune evasion." (PMID 35432344, 2022). "Targeting of SETDB1 with a small-molecule inhibitor synergized with MAPK inhibition in sensitive cell lines and induced cell death in MAPKi-resistant melanoma cell lines." (PMID 36497341, 2022). "Among others, the lysine methyltransferase SETDB1 known to methylate histone H3 lysine 9 (H3K9), was shown to accelerate melanoma formation." (PMID 32046099, 2020). "During exposure to chemotherapeutics or targeted therapies, we observed the consistent upregulation of SETDB1 and SETDB2 in melanoma, lung and colon cancer-derived cell lines, which indicates a common role for both proteins following drug exposure." (PMID 30850015, 2019). "We have reported that the increase in H3K9me3 is derived from the methyltransferases SETDB1 and SETDB2 following treatment in melanoma, lung, breast and colorectal cancer cell lines, as well as melanoma patient data." (PMID 30850015, 2019). "Higher expression of SETDB1, SETDB2 and H3K9me3 was confirmed at the protein level in four IDTC models representative of melanoma, lung and colon cancer." (PMID 29492189, 2018). "The other two histone methyltransferases (HMTs), SETDB1 and Histone-lysine N-methyltransferase SUV39H1 (SUV39H1), also cooperate with BRAF V600E to accelerate the incidence and severity of melanoma development in fish." (PMID 30544544, 2018). "Using a zebrafish melanoma model, evidence was provided that SET Domain B1 (SETDB1) cooperates with BRAFV600E to induce melanoma formation." (PMID 29156643, 2017). "The histone methyltransferase, SETDB1, is also upregulated in melanoma but not in benign nevi and normal melanocytes." (PMID 39624739, 2024). "In melanoma, KDM5B recruits SETDB1 to repress its targets and further promotes immune evasion." (PMID 38317200, 2024). "Finally, although mechanistically unclear, SETDB1 and KDM5B demonstrate pleiotropic effects in melanoma targeted therapy and immunotherapy which demand deeper mechanistic exploration." (PMID 36497341, 2022). "In this study, SETDB1 was found to form a complex with other H3K9 methyltransferases, such as SUV39H1, and they acted together to alter gene transcription in a manner that promotes onset and invasiveness of melanoma." (PMID 36582533, 2022). "The tumorigenic effects of SETDB1 are attributed to the regulation of Thrombospondin 1 (THBS1), which promotes melanoma invasiveness and metastasis as well as downregulation of the expression of DOPAchrome tautomerase (DCT), an enzyme that participates in melanin synthesis." (PMID 34440561, 2021).
melanoma (continued). "Interestingly, expression of SETDB1, as well as SETDB2, was also upregulated in other acquired resistance models for melanoma, lung, breast, and colon cancer." (PMID 32046099, 2020). "While SETDB1 was recently established as a bona fide amplified cancer driver in melanoma and lung cancer, the role of NSD3/WHSC1L1 has not been well characterized and so we further validated its oncogenic role in vitro (below)." (PMID 24874471, 2014). "However, 1 notable exception was melanoma (SKCM), which despite being one of the cancer types with the strongest NNMT-total HMT relationships exhibited a far stronger anticorrelation of NNMT to the euchromatic H3K9me3 writer SETDB1." (PMID 37883365, 2023). "However, despite the clear impact of KDM5B and SETDB1 on immune evasion, there have not been any studies on the effects of their inhibition in melanoma resistance to immunotherapies." (PMID 35515106, 2022). "Interestingly, melanoma cells harboring low levels of SETDB1 were not affected by treatment with epigenetic inhibitors, underscoring SETDB1’s role as a valuable therapeutic target in CM." (PMID 34575678, 2021). "SETDB1 gene copy number amplification (CNA) has been frequently observed in various cancers, including melanoma, lung SCLC, and NSCLC, hepatocellular carcinoma, and breast cancer; a strong correlation between SETDB1 overexpression and cancer development has been detected in various cancers." (PMID 33343623, 2020).
breast cancer (51 papers, 2014 to 2026). A primary or metastatic malignant neoplasm involving the breast. "We focused on the association between SETDB1 expression and the breast cancer, ovarian cancer, lung cancer, and gastric cancer prognosis." (PMID 35656340, 2022). "SETDB1 was shown to regulate and influence normal cellular homeostasis, while it is also implicated in breast cancer formation; however, its role in metastasis is rather less well understood." (PMID 31405032, 2019). "Additionally, SETDB1 overexpression has been associated with Luminal B and triple-negative molecular subtypes of breast carcinoma." (PMID 41503337, 2025). "Cardamonin could suppress the expression of multiple stem cell-associated histone modifying genes including SETDB1, and prevent the enrichment of breast cancer stem-like cells when combined with chemotherapeutic drugs." (PMID 36582533, 2022). "Taken together, these data hinted that abnormal expression of SETDB1 might be associated with the progression of breast cancer." (PMID 30309377, 2018). "LINC00115 functions as a scaffold molecule to control the SETDB1/PLK3/HIF1α signaling pathway in paclitaxel-resistant breast cancer stem cells." (PMID 41614928, 2026). "This study establishes dual aptamers-based PROTACs targeting SETDB1, offering effective therapeutic strategies for breast cancer treatment." (PMID 41498743, 2026). "A novel strategy for overcoming treatment resistance in breast cancer is to target LINC00115 or SETDB1 to modulate HIF-1α signaling." (PMID 41614928, 2026). "SETDB1 plays an oncogenic role in various human cancers, specifically related to breast cancer endocrine therapy resistance." (PMID 38520019, 2024). "At the TP53BP2 gene promoter in HeLa cells and the RASSF1A gene promoter in MDAMB-231 breast cancer cells, SETDB1 interacts preferentially with the de novo DNA methyltransferase DNMT3A, but not with the maintenance methyltransferase DNMT1." (PMID 38904842, 2024). "In breast cancer, SETDB1 binds to Snail promoter and increases its expression and then promoting the EMT of MCF7 cells." (PMID 38317200, 2024). "Our findings uncover LINC00115 as a critical regulator of BCSC and highlight targeting LINC00115 and SETDB1 as a potential therapeutic strategy for chemotherapeutic resistant breast cancer." (PMID 38520019, 2024). "SETDB1 is an oncogene in breast cancer and play an important role in the treatment of endocrine therapy resistance." (PMID 39372872, 2024). "Consistent with the previous report that SETDB1 is an oncogene in breast cancer and plays an important role in treating endocrine therapy resistance, our study reveals that SETDB1 is critical for BCSC properties, chemotherapy resistance, and metastasis." (PMID 38520019, 2024). "Studies have shown that HOTAIR-mediated direct inhibition of miR-7 in breast cancer stem cells can upregulate SETDB1 and inhibit E-cadherin, thus favoring EMT." (PMID 39583200, 2024). "Methyltransferase SETDB1 regulates the progression of breast cancer and its chemotherapy resistance through complex interactions with various molecules." (PMID 37220590, 2023). "Low expressions of TPT1/TCTP and SETDB1 are correlated in leading to a better prognosis of breast cancer and colon cancer patients, respectively, which supports clinical benefits of the IO relationship normalization." (PMID 37269056, 2023). "A previous report has revealed that miR-381 directly targets and suppresses SETDB1 to inhibit breast cancer cell proliferation." (PMID 35184652, 2022). "This study suggests that the PELP1/SETDB1 axis play an important role in aberrant Akt activation and serves as a novel target for treating endocrine therapy resistance in breast cancer." (PMID 35395812, 2022). "Further analysis using the KEGG pathway database confirmed that down-regulated genes upon SETDB1-KD were involved in ER-signaling, breast cancer, and PI3K-Akt signaling." (PMID 35395812, 2022).